IL1B (interleukin 1 beta)
Diseases named in the same sentence as IL1B in open-access papers (continued):
Sharing a sentence is not in itself a finding about the gene and the disease.
nephrotic syndrome (6 papers, 2013 to 2024). A collection of symptoms that include severe edema, proteinuria, and hypoalbuminemia; it is indicative of renal dysfunction. "Nephrotic syndrome is consistently associated with elevated levels of serum IL-2, IL-2R, IFN-γ, and TNF-α and normal levels of IL-1α, IL-1β, and IFN-α." (PMID 38127456, 2024). "Glomeruli isolated from mice with nephrotic syndrome also had increased expression of IL-1β and TNF RNA." (PMID 23382978, 2013). "The expression of NLRP3, Casapase-1, GSDMD, IL-1β, and α-SMA in the renal tissue of nephrotic syndrome rats increased, E-cadherin decreased, and Tunel staining showed that an increase of renal tubular epithelial cells with broken nuclei." (PMID 38995910, 2024). "Although IL-1β was described to be a major proinflammatory mediator in children with nephrotic syndrome and in animal models of nephrosis, in the present study no variations were observed in IL-1β expression levels in PAN-treated rats compared to the control group." (PMID 29607318, 2018).
Opportunistic infection (6 papers, 2007 to 2025). An infection that is caused by a pathogen that would generally not be able to cause an infection in a host with a normal immune system. "This is of particular relevance when considering that in a targeted anti-NLRP3 therapy, other pathogen-recognizing inflammasomes can be engaged to produce IL-1β, thus reducing the risk of immune suppression and opportunistic infections." (PMID 34513923, 2021). "Within the context of targeting IL-17A or IL-1β in the clinic, one has to keep in mind that altering proinflammatory immune responses harbors the risk of interfering with the control of acute infection and of susceptibility to opportunistic infections." (PMID 24918427, 2014). "Cryptococcal meningitis, which is an opportunistic infection, may exacerbate this inflammatory state, leading to IL-1β-driven leukocyte mobilization." (PMID 41425969, 2025). "In elderly individuals, Zn supplementation has been associated with a non-significant increase in IL-1β levels alongside a lower incidence of opportunistic infections." (PMID 37892471, 2023).
pemphigus (6 papers, 2019 to 2025). Pemphigus is a group of rare autoimmune diseases that cause blistering of the skin and mucous membranes (mouth, nose, throat, eyes, and genitals).This conditioncan occur at any age, but often strikes people in middle or older age. "Research indicates that untreated patients with active pemphigus have high levels of IL-1β in their serum and tissues, but patients in remission have low levels." (PMID 40102153, 2025). "They discovered that animals with reduced IL-1β production had a lower incidence of pemphigus than the control group." (PMID 40102153, 2025). "It is thus intriguing that the increase of Flavonifractor and positive correlation between Flavonifractor and circulating inflammatory markers (C5a, IL-6, IL-8, IL-7, IL-1β and IL-21) were reported in pemphigus vulgaris, a subgroup of pemphigus." (PMID 38022583, 2023). "Relative to patients with active pemphigus, those experiencing complete remission following rituximab displayed under-expression of IL-1β and the CD27 memory marker genes." (PMID 33505392, 2020). "The increased expression of IL-1β may directly contribute to the inflammation and damage process in pemphigus." (PMID 40102153, 2025). "This suggests that IL-1β promotes the occurrence or development of pemphigus." (PMID 40102153, 2025). "Overall, this study showed that self-reactive and non-self-reactive B cell populations from pemphigus patients do not express the same genes during the acute phase of the disease, in particular genes encoding for IL-1β, IL-12p35, IL-23p19, and IRF5." (PMID 31440235, 2019). "In order to evaluate the consequences of the decreased IL-1β gene expression in DSG-positive B cells from pemphigus patients whether they were treated with corticosteroids or rituximab, we performed longitudinal dosages of serum IL-1β using ELISA assay." (PMID 31440235, 2019). "Interestingly, the expression of the IL-1β gene in DSG-positive B cells, which was higher at baseline in pemphigus patients than in healthy individuals (12 vs. 6%, p = 0.048), returned to normal values after rituximab treatment (12 vs. 4%, p = 0.039)." (PMID 31440235, 2019). "We observed a non-significant decrease of serum IL-1β ELISA values in pemphigus patients during the first 3 months of treatment, that was secondarily followed by a re increase of serum levels to baseline values when corticosteroids doses were tapered during patients' follow-up." (PMID 31440235, 2019).
periapical granuloma (6 papers, 2018 to 2025). Chronic nonsuppurative inflammation of periapical tissue resulting from irritation following pulp disease or endodontic treatment. "We found that IL-1α and IL-1β expression levels were both associated with the inflammation grade in periapical granulomas (P < 0.05)." (PMID 30012121, 2018). "Subsequently, immunohistochemical (IHC) staining unraveled elevated IL-1β expression in radical cysts (RCs) relative to periapical granulomas (PGs), whereas the expression levels of Mertk, Gas6, and IL-10 were more pronounced in PGs than in RCs." (PMID 41155449, 2025). "Specifically, IL-1β expression was higher in radical cysts (RCs) than in periapical granulomas (PGs), while the expression of IL-10 was stronger in PGs than in RCs." (PMID 38612664, 2024). "The pro-inflammatory characteristic of periapical granulomas has been established; increased IL-1β, IL-6 and TNF-α has been documented." (PMID 35053012, 2021). "Radicular cysts were characterized by a higher production of the pro-inflammatory cytokine IL-1β, as compared with periapical granulomas." (PMID 35053012, 2021). "The pro-inflammatory characteristic of periapical granulomas has been established; increased IL-1β, IL-6 and TNF-α has been documented in symptomatic APs versus asymptomatic APs." (PMID 35053012, 2021). "In our study, we found that IL-1α and IL-1β levels increased in the moderate and severe inflammatory cell infiltration subgroups of periapical granulomas." (PMID 30012121, 2018). "In summary, the pro-inflammatory cytokines IL-1α and IL-1β are expressed in both periapical granulomas and radicular cysts in primary teeth." (PMID 30012121, 2018). "ELISA results showed that IL-1α and IL-1β levels were higher in the periapical granuloma group than in the radicular cyst and normal control groups (P < 0.05)." (PMID 30012121, 2018). "Immunohistochemistry results showed that both IL-1α and IL-1β were expressed in periapical granulomas and cysts." (PMID 30012121, 2018). "Our immunohistochemistry results showed that positive IL-1α and IL-1β staining was found not only in the inflammatory cells but also in the epithelial cells and on the vascular endothelium in both periapical granulomas and radicular cysts from primary teeth." (PMID 30012121, 2018). "A significant positive correlation was observed between the protein expression levels of IL-1α and IL-1β and the inflammation grade in periapical granulomas from primary teeth (P < 0.05)." (PMID 30012121, 2018). "Our data support that IL-1α in periapical granulomas from primary teeth was positively correlated with IL-1β." (PMID 30012121, 2018). "Our results showed that IL-1α and IL-1β were both expressed in periapical granulomas and radicular cysts." (PMID 30012121, 2018). "It seems that a synergic effect of IL-1α and IL-1β exists in the progression of periapical granulomas in primary teeth." (PMID 30012121, 2018). "The relationships between the IL-1α and IL-1β protein expression levels and the inflammation grade in periapical granulomas from primary teeth were analysed by Spearman’s rank correlation." (PMID 30012121, 2018). "Expression levels of the cytokines IL-1α and IL-1β in periapical granulomas from primary teeth increased with increasing inflammatory severity and appeared to be a contributing factor to the progression of periapical lesions." (PMID 30012121, 2018). "Furthermore, expression levels of the cytokines IL-1α and IL-1β in periapical granulomas in primary teeth increased with increasing inflammatory severity and appeared to be a contributing factor to periapical lesion progression." (PMID 30012121, 2018). "Moreover, a significant positive correlation was observed between the protein expression levels of IL-1α and IL-1β in periapical granulomas from primary teeth (P < 0.01)." (PMID 30012121, 2018).
periapical granuloma (continued). "In addition, the cytokines IL-1α and IL-1β are abundantly expressed in periapical granulomas, and these high levels of IL-1α and IL-1β expression are consistent with the inflammation severity." (PMID 30012121, 2018). "Particularly, our data from periapical granulomas from primary teeth showed a positive correlation between IL-1α and IL-1β expression levels and the inflammation grade, suggesting that increased IL-1α and IL-1β expression occurred parallel to the severity of the inflammation." (PMID 30012121, 2018). "Immunohistochemical analysis showed strong positivity for SOCS-1 and IL-1β in the lesions classified as periapical cyst, while the lesions diagnosed as periapical granuloma were not labelled." (PMID 41388504, 2025).
pneumococcal pneumonia (6 papers, 2021 to 2025). A febrile disease caused by STREPTOCOCCUS PNEUMONIAE. "Increased levels of IL‐1β were positively correlated with the susceptibility to pneumococcal pneumonia (OR, 4.12; 95% CI, 2.96–5.28; p = 0.017)." (PMID 40501500, 2025). "Immune cells including macrophages can trigger acute inflammation and secrete IL-1β, which plays an important role in protecting the host from pneumococcal pneumonia." (PMID 33918100, 2021). "During pneumococcal pneumonia in mice, high levels of IL-6, IL-1β and TNF-α are produced in the early stages of lung parenchyma and/or bronchoalveolar space infection." (PMID 34925324, 2021). "Thus, in line with our in vitro findings, in vivo expression of KLF4 in myeloid cells increases the release of the pro-inflammatory cytokines TNF-α, KC and IL-1β and decreases the release of the anti-inflammatory cytokine IL-10 in murine pneumococcal pneumonia." (PMID 34589087, 2021).
pneumoconiosis (6 papers, 2009 to 2025). An occupational lung disorder caused by inhalation of dust particles. "A study reported that carriers of the IL-1β -511 TT genotype markedly increased the pneumoconiosis risk in the Russian population." (PMID 40182855, 2025).
polyarthritis (6 papers, 2018 to 2025). "Similarly, docetaxel has recently been reported to reduce disease progression and joint destruction in rat polyarthritis models, an effect associated with the suppression of key inflammatory cytokines like TNF-α and IL-1β." (PMID 41614803, 2025).
postpartum depression (6 papers, 2018 to 2025). A type of clinical depression that occurs after childbirth. "Some studies have shown that IL-1β levels in depressed patients are elevated and positively correlated with the degree of illness in elderly depressed patients and in women with postpartum depression." (PMID 40077572, 2025). "Mangiferin treatment suppresses microglial activity and downregulates the levels of TNF-α, IL-6, and IL-1β in the hippocampus of mice with postpartum depression." (PMID 38915473, 2024). "Hypericin, one of the rich compounds in CS extract, has been reported to be able to alleviate the symptoms of postpartum depression as effective as fluoxetine by decreasing the levels of inflammatory factors (IL-6, IL-1β, TNF - α) in serum." (PMID 36909192, 2023). "It is worth emphasizing that the serum proinflammatory cytokines, including IL-1β and IL-6, were also increased in the rats with postpartum depression." (PMID 30390665, 2018). "The potential for IL-1β to serve as a biomarker for postpartum depression could have significant clinical implications." (PMID 40682534, 2025). "However, the serum proinflammatory cytokines, including IL-1β and IL-6, were increased in the rats with postpartum depression." (PMID 30390665, 2018).
pressure ulcers (6 papers, 2015 to 2025). "In stage 1 pressure ulcers on the sacrum, IL-1β, IL-6, IL-8, TNF-α and IFN-γ were found to be upregulated." (PMID 39772735, 2025). "At day 6 post‐I/R, H2 treatment significantly reduced the relative mRNA and protein expression of TNF‐α, IL‐1β, IL‐6 and IL‐8 in wounded tissue, and their expression was lowest in pressure ulcer mice treated with 75% H2." (PMID 29921037, 2018). "Prolonged up-regulation of IL-1β, and IL-6 might enhance local inflammation, and continuous local inflammation may contribute to the pressure ulcer formation." (PMID 26177082, 2015). "IL-1β and IL-6 were increased in preference of other cytokines, which may indicate a superior role of IL-1β and IL-6 in the formation of pressure ulcers." (PMID 26177082, 2015). "The concentrations of IL-1β, IL-6, and TGF-β in blood and wounds were all significantly elevated in response to pressure ulcers while the activation of KLF4 significantly suppressed the expression of these cytokines." (PMID 34568499, 2021). "Similar to mupirocin, mice treated with oral clindamycin exhibited a decrease in expression of IL-1β (−1.32-fold change), MMP-2 (−1.37-fold change), and TNF-α (−2.80-fold change) in infected pressure ulcers." (PMID 34035383, 2021). "With an impaired wound healing environment, i.e. pressure ulcers in the elderly, decreased GM-CSF signaling leads to lower expression of nucleotide-binding domain-like receptor protein 3 (NLRP3) and reduced neutrophil interleukin-1 beta (IL-1β), resulting in impaired innate immune responses." (PMID 36685591, 2022).
proliferative diabetic retinopathy (6 papers, 2007 to 2023). Advanced retinopathy due to diabetes mellitus characterized by the formation of new vessels in the retina. "We detected up-regulated levels of VEGF-A (p = 0.001), PIGF (p<0.001), Angiopoietin-1 (p = 0.005), Angiopoietin-2 (p<0.001), IL-1β (p = 0.012), and IL-8 (p = 0.018) in proliferative diabetic retinopathy samples." (PMID 36662891, 2023). "The levels of cytokines, including IL-1β, IL-6 and IL-8, are increased in the vitreous of patients with proliferative diabetic retinopathy and in the retina from diabetic rats and mice." (PMID 17437639, 2007).
Psoriasiform dermatitis (6 papers, 2016 to 2026). A skin abnormality characterized by redness and irritation, with thick, red skin that displays flaky, silver-white patches (scales). "To further validate that brusatol exerts its therapeutic effects by targeting IL-1β, we conducted a loss-of-function rescue paradigm in mice with IMQ-induced psoriasiform dermatitis." (PMID 41508030, 2026). "Topical genistein ameliorated the murine IMQ-induced psoriasiform dermatitis with the reduction of skin score, epidermal thickness, and of IL-1β, IL-6, TNF-α, CCL2, IL-17, and IL-23 expression in the skin lesions." (PMID 32751360, 2020). "The high-fat diet rich in SFAs exacerbates the IMQ-induced psoriasiform dermatitis in mice; SFAs activate nucleotide-binding domain, leucine-rich repeats containing family, pyrin domain-containing-3 (NLRP3) inflammasome which generates active IL-1β and IL-18 in CD11c+ macrophages." (PMID 32751360, 2020).
pterygium (6 papers, 2018 to 2024). A wedge-shaped fibrovascular lesion arising from the bulbar conjunctiva and extending to the cornea. "Among these cytokines, IL-1β was associated with extracellular matrix remodeling, angiogenesis, and fibroblast proliferation by activating pterygium body fibroblasts." (PMID 39682531, 2024). "The researchers emphasized the need for future studies to investigate other polymorphisms or haplotypes of TNF-α and IL-1β to better assess genetic susceptibility to pterygium formation and recurrence." (PMID 39682531, 2024). "They concluded that IL-1β-mediated inflammation plays a significant role in the development of both primary and recurrent pterygium." (PMID 39682531, 2024). "Other cytokines (IL-6, IL-8, IL-1β) were detected at similar levels in primary and recurrent pterygium." (PMID 39682531, 2024). "Further observation in our study revealed that MMC clearly decreased the protein levels of IL-1β in the pterygium specimens." (PMID 31827916, 2019). "Further results demonstrated that MMC injection can significantly inhibit the activation of the NLRP3/Caspase-1 pathway in pterygium tissues and thus decrease the expression of IL-1β and IL-18." (PMID 31827916, 2019). "Functional IL-18 and IL-1β cause all sorts of changes, such as fibrosis, EMT, apoptosis, and abnormal cell proliferation, all of which are included in mechanisms of pterygium genesis." (PMID 29724886, 2018). "The expression of nod-like receptor pyrins-3 (NLRP3), caspase-1, IL-18, and IL-1β was analyzed in 60 human pterygium tissues and 60 human conjunctival epithelium tissues using real-time quantitative polymerase chain reaction (qRT-PCR) and Western blot analysis." (PMID 29724886, 2018). "Other cytokines (IL-6, IL-8, IL-1β, and TGF-β1) were detected at similar levels in both primary and recurrent pterygium (p = 0.2986)." (PMID 39682531, 2024). "Previous study also shows that IL-1β promotes the matrix metallopeptidase-9 (MMP-9) production and migration of pterygium fibroblasts." (PMID 36768371, 2023). "The protein levels of these factors were highly expressed in pterygium samples compared with normal conjunctiva samples with statistical difference (NLRP3, caspase-1, and IL-1β: P<0.05)." (PMID 29724886, 2018). "The mRNA of these factors was highly expressed in pterygium samples with statistical difference (NLRP3: P<0.001; caspase-1: P<0.001; IL-1β: P<0.05; IL-18: P<0.01)." (PMID 29724886, 2018). "Thirty pterygium samples and thirty normal conjunctiva samples were collected and analyzed for NLRP3, caspase-1, IL-18, and IL-1β mRNA expression using qRT-PCR." (PMID 29724886, 2018). "Another 30 pterygium samples and 30 normal conjunctiva samples were detected for NLRP3, caspase-1, pro-IL-1β, and IL-1β protein level with Western blot analysis." (PMID 29724886, 2018). "For instance, CASP1 could participate in pyroptosis through activated IL1B and IL18, and FASLG could be involved in pterygium fibroblasts, suggesting that they might play a role in pterygium pathogenesis." (PMID 38732006, 2024). "However, no study has yet investigated IL-1β levels across various types of pterygium." (PMID 39682531, 2024).
pyelonephritis (6 papers, 2009 to 2025). An inflammatory process affecting the kidney. "We therefore evaluated the diagnostic utility of the urinary MIF, IL-1β, and KIM-1 levels as biomarkers for AKI during kidney infection." (PMID 23319831, 2012). "Nevertheless, experimental models of pyelonephritis indicate more complex properties of IL1β." (PMID 35604916, 2022). "In the pyelonephritis group, median IL-1β was 32.3 pg/ml (range 1.63 to 70.2) and in the lower UTI group, median IL-1β was 1.64 pg/ml (range 0 to 14.55), P < 0.001." (PMID 19707519, 2009). "The magnitude of IL-1β-driven OAT1/3 downregulation at 0.1 ng/mL agrees quantitatively, in terms of directionality and magnitude expected for a reduction in basal uptake, with what we observed in vivo during active pyelonephritis." (PMID 41394604, 2025). "Notably, measured plasma cytokines in that cohort were toward the low end of pathophysiological ranges (<0.1 ng/mL), and plasma IL-1β concentrations were not significantly elevated during active pyelonephritis." (PMID 41394604, 2025).